HMMR (hyaluronan mediated motility receptor)
Diseases named in the same sentence as HMMR in open-access papers (continued):
Sharing a sentence is not in itself a finding about the gene and the disease.
tumor (continued). "Here, we propose that AURKA represents a rational therapeutic target for MPNSTs and that the sensitivity of these tumours to AKI may be regulated by gene dosage and expression of HMMR/RHAMM." (PMID 23328114, 2013). "Importantly, LUAD cells lacking HMMR expression lose their capacity for tumor initiation and distant metastasis." (PMID 38293522, 2024). "UBE2S, HMMR, TMPRSS11E and KRT6A were found to be up-regulated in tumor tissues relative to surrounding non-cancerous and normal tissues in the screening cohort." (PMID 37199651, 2023). "Also, Tregs from NI ad I TDLN share CD58, ITGAM, MCAM, CEACAM4, SELPLG, and HMMR expression, which could ensure recirculation among TDNLs; and Tregs from I TDLN and tumor Tregs share ICAM1 expression, which could be responsible for the migration among tissues with presence of tumor cells." (PMID 32601304, 2020). "In univariate analyses, lymph node positivity, surgical margin positivity, non-localized tumor, age at prostatectomy, and biomarkers CCND1, HMMR, IGF1, MKI67, SIAH2, and SMAD4 in malignant epithelium were significantly associated with time to BF." (PMID 24708576, 2014).
cancer (137 papers, 2008 to 2026). A tumor composed of atypical neoplastic, often pleomorphic cells that invade other tissues. "HMMR, first identified as a receptor for hyaluronic acid, has been implicated in a wide range of cancers with high expression correlated to poor outcomes." (PMID 41550726, 2026). "Research has shown that HMMR is frequently overexpressed in numerous cancers and is linked to adverse clinical features and poor prognosis." (PMID 39990663, 2025). "Several variants of HMMR have been reported, and these polymorphisms have been linked to various cancer types." (PMID 40567905, 2025). "The HMMR gene is associated with an increased risk of early-onset BC and contributes to cancer progression through the control of cell growth and cancer spread to other parts of the body." (PMID 40941673, 2025). "High expression of HMMR is usually detected in highly proliferative tissues and is associated with poor disease outcomes in a variety of cancers." (PMID 39086352, 2024). "One oncogenic signaling hub that has been implicated in the metastases of breast and other cancers is the multifunctional, intracellular/extracellular protein, RHAMM (gene name HMMR)." (PMID 37349798, 2023). "The potential role of HMMR in cancer development and progression is linked to two main functions, namely HA-induced cell migration and cell cycle progression." (PMID 37673961, 2023). "Some studies showed that a high expression of HMMR is associated with worse prognosis as it promotes cancer growth and metastasis." (PMID 33763352, 2021). "HMMR is also associated with neoplastic processes and its role in cancer progression is often attributed to hyaluronan-mediated signaling." (PMID 32231069, 2020). "HMMR, which was associated with cell movement, was expressed at low levels in the normal tissue, whereas it was highly expressed in tissues with active proliferation such as the testes and cancers." (PMID 38633247, 2024). "However, due to the involvement of HMMR in mitosis, most HMMR mutations are associated with familial cancers in humans (based on ClinVar data)." (PMID 38904660, 2024). "Although the status of universal upregulation for the Hyaluronan-Mediated Motility Receptor (HMMR) in pan-cancer is still unknown, HMMR is upregulated and associated with poor prognosis for some tumors." (PMID 36704516, 2022). "Moreover, an HMMR splice variant that loses microtubule binding activity is expressed at an elevated level in a variety of cancers." (PMID 32231069, 2020). "However, HMMR (in combination with CD44) has been hypothesised to play an important role in cancer-associated fibroblast migration." (PMID 34199452, 2021). "HMMR coding a 724 amino acids protein, which may associate with the motility of cancer cells." (PMID 34721973, 2021). "Accumulating clinical evidence demonstrates that HMMR overexpression correlates strongly with poor prognosis across multiple cancer types." (PMID 41488674, 2025). "HMMR also has oncogenic roles in several other human cancer systems, sustaining cell proliferation, survival and migration in cells derived from cancers of brain, lung, ovary, prostate, head and neck and breast." (PMID 41253884, 2025). "Recent studies have revealed that HMMR expression plays a crucial role in proliferation and metastasis in different types of cancer such as prostate, breast, and head and neck carcinomas." (PMID 39859458, 2025). "Due to the persistent overexpression of HMMR in cancer and its manifold functions in cancer initiation and advancement, it holds substantial promise as a target for cancer treatment." (PMID 38576486, 2024). "HMMR, also known as CD168 and located on chromosome 5, plays a multifaceted role in cancer progression." (PMID 38740918, 2024). "HMMR’s association with key cell cycle regulators (AURKA, TPX2, and CDK1) underscores its pivotal role in cancer initiation and advancement." (PMID 38576486, 2024).
cancer (continued). "SNHG15, hsa.miR.130a.3p, PTTG1, INSR and HMMR were described in a ccRCC environment, exhibiting the higher expression that induces metastasis and promotes cancer development." (PMID 38673800, 2024). "The fine-tuned regulation of HMMR in healthy tissues contrasts with its upregulation in proliferative tissues, particularly evident in various cancer types." (PMID 38576486, 2024). "This study not only contributes to the understanding of HMMR’s role in cancer but also suggests novel therapeutic strategies." (PMID 38576486, 2024). "It was revealed that HMMR was highly upregulated in all carcinomas, including ESCA, COAD, CESC, and READ, followed by BRCA and STAD." (PMID 38576486, 2024). "Intraglandular and zonal hMMR nuclear protein expression was registered in seven (58%) of a total of twelve cancers." (PMID 36984490, 2023). "Highly expressed miR-34a-5p induces LUAD cell apoptosis and inhibits cancer cell proliferation by targeting HMMR." (PMID 36447119, 2023). "Consistent with previous studies, HMMR affects cancer cell proliferation and epithelial-to-mesenchymal transition and results in a poor prognosis." (PMID 35311097, 2022). "Previous studies have shown that HMMR plays crucial roles in tissue homeostasis, neural development, and cancer progression." (PMID 35311097, 2022). "HMMR was upregulated in some cancer tissues and was correlated with adverse clinicopathological features and poor prognosis." (PMID 35311097, 2022). "The binding of HA to its receptor HMMR can activate a series of downstream intracellular pathways, thus promoting cancer cell proliferation and invasion." (PMID 36002694, 2022). "Elevated HMMR expression is a feature of most cancers and is also an indicator of poor prognosis in many cancers." (PMID 36275729, 2022). "In the functional assay, depletion of HMMR significantly repressed the cancer cell growth and migration of LUAD." (PMID 35311097, 2022). "Previous studies indicate that the HMMR is overexpressed in and is a potential prognostic factor in various cancer types, including breast cancer, head and neck squamous cell carcinoma, hepatocellular carcinoma, and other cancers." (PMID 34765644, 2021). "We observed that HMMR mRNA expression was significantly higher in most human cancers compared with the corresponding normal tissues." (PMID 34527588, 2021). "In contrast, for some cancers, such as malignant peripheral nerve sheath tumors 13, 14 and seminomas 15, HMMR expression is downregulated and its low expression associates with poor patient survival." (PMID 33061798, 2020). "HMMR over-expression in immortalized cancer cells induces phenotypes consistent with an increase in active Ran including defects in spindle orientation." (PMID 28994651, 2017). "As HMMR is known to regulate the cell division axis in immortalized cancer cells, we next examined the localization of HMMR and the axis of NP cell division during neurogenesis in E14.5 embryos." (PMID 28994651, 2017). "Collectively, these observations raise a strong possibility that FAM83D coordinates cell cycle progression in human cancer cells by binding with HMMR, TPX2, and AURKA." (PMID 29088801, 2017). "HMMR/RHAMM (CD168) is a hyaluronan-mediated motility receptor and cell surface oncogenic protein that is commonly upregulated in human cancers." (PMID 24489730, 2014). "Moreover, HA can also interact with hyaluronan-mediated motility receptor (RHAMM), further enhancing cancer cell selectivity." (PMID 40862923, 2025). "Although more detailed mechanistic investigations need to be undertaken, the findings in this study reveal a potential new function of HMMR in cancer progression and provide new targets that may overcome chemotherapy resistance." (PMID 39086352, 2024). "Therefore, in this regard, the versatile functions of HMMR, both extracellularly and intracellularly, underscore its significance in cancer biology." (PMID 38576486, 2024).
cancer (continued). "HMMR’s involvement in microtubule assembly and cellular interactions, both extracellularly and intracellularly, provides critical insights into its contribution to cancer cell processes." (PMID 38576486, 2024). "Due to persistent HMMR overexpression in cancer, it emerges as a promising therapeutic target." (PMID 38576486, 2024). "Given that HMMR was overexpressed in pan-cancer, we further analyzed its prognosis in pan-cancer." (PMID 35311097, 2022). "Besides, the function of HMMR on cancer cell proliferation and migration was examined using cell growth curve and colony formation, Transwell, and wound healing assays." (PMID 35311097, 2022). "Finally, we found that HMMR was highly expressed in diverse cancer cell lines, including LUAD cell lines." (PMID 35311097, 2022). "HMMR is a multifunctional protein that regulates cancer progression." (PMID 36275729, 2022). "The expression of HMMR was reported to be upregulated in several cancer types, but it was also downregulated in other cancer types than in normal controls based on the results from the LAML and TGCT projects." (PMID 34765644, 2021). "Tissue cells and cancer cells with HMMR overexpression tend to be highly proliferative." (PMID 33061798, 2020). "This review supports the designation of HMMR as a homeostasis, mitosis, and meiosis regulator, and clarifies how its dysfunction may promote the tumorigenic process and cancer progression." (PMID 32231069, 2020). "Hyaluronan-mediated motility receptor (HMMR) is a regulator of homeostasis, mitosis, and meiosis, and its dysfunction may promote tumorigenesis and cancer progression." (PMID 33029143, 2020). "Hyaluronan-mediated motility receptor (RHAMM), also known as CD168, is an HA-binding protein and has been implicated in mitotic spindle formation/stability, correlated with poor outcomes in many cancers, and is implicated in metastasis." (PMID 29137675, 2017). "From this transcriptional gene data, we show that overexpression of ANXA4 regulates genes that are known to be related to cancer, for example the activation of hyaluronan mediated motility receptor (RHAMM), AKT, and cyclin-dependent kinase 1 (CDK1) as well as the suppression of p21." (PMID 22970268, 2012). "Taken together, these results suggest that HMMR may serve as an oncogene in human cancers." (PMID 35311097, 2022). "Primarily, these results confirm that HMMR may play a crucial role in human cancer progression." (PMID 35311097, 2022). "In addition, HMMR was found to be functional in a variety of cancers." (PMID 34692489, 2021). "As the HMMR and AURKA-TPX2-TUBG1 gene products are functionally related in the regulation of mammary epithelial polarization, the associations between variants at these loci that were included on the iCOGS array and cancer risk in BRCA1/2 mutation carriers were assessed." (PMID 25830658, 2015). "Among the SHRPI components, G6PD, HMMR, and NEIL3 were predominantly expressed in cancer cells, with G6PD showing the highest expression proportion." (PMID 41050691, 2025). "HMMR depletion in KA5, KA14 and KA16 inhibited their proliferative expansion compared to KELLY and KC17, agreeing with a similar role in other cancer cell types 7,8." (PMID 41253884, 2025). "Hyaluronan-mediated motility receptor (HMMR) is overexpressed in multiple carcinomas and influences the development and treatment of several cancers." (PMID 38633247, 2024). "Resveratrol (RES) can inhibit the interaction of HMMR and SLC7A11 to mediate cancer cell ferroptosis." (PMID 38288118, 2023). "HMMR, also known as RHAMM, is one of the main HA receptors also plays vital role in cancer progression." (PMID 36002694, 2022). "Liver hepatocellular carcinoma patients who were with advanced cancer stages inclined to have the higher mRNA expression levels of CDK1, HMMR, PTTG1, and TTK." (PMID 34187556, 2021). "HMMR and KIF20A are important regulators of mitosis and exhibit oncogenic properties in various cancers through multiple mechanisms." (PMID 34556750, 2021).
cancer (continued). "Previous literature clearly indicates that HMMR and KIF20A function as oncogenes in many types of cancers." (PMID 34595101, 2021). "Overexpression of HMMR is associated with cancer growth, migration, and poor prognosis in various cancers, including HCC, via its stimulation of the hyaluronan-HMMR signaling cascade in addition to its oncogenic activities." (PMID 32514252, 2020). "We find that FMOD activates ERK to promote BCCMI, which is reminiscent of hyaluronan mediated motility receptor (RHAMM) promoting BCCMI via activation of ERK, and undergoes the important part that ERK plays in cancer metastasis." (PMID 31824307, 2019). "As known, hyaluronic acid and its derivatives can bind to specific receptors on external of cancer cells, owing to their high expression, for instance, CD44 receptors, hyaluronan-mediated motility receptor (HMMR) and so on." (PMID 31571501, 2019). "The strongest overexpressed proteins in treated Caco-2 exosomes (eg, CD59, CRP, CTSD, HMMR, TRIM22) are involved as potential oncogenes in the pathogenesis of different cancers, including CRC." (PMID 25594007, 2014). "Hyaluronan-mediated motility receptor (HMMR), originally identified as a hyaluronan-binding protein, has gained increasing recognition as a multifunctional oncoprotein involved in cell cycle regulation, mitotic spindle formation, and cancer progression." (PMID 41488674, 2025). "Altogether, RRM2, CCNB1, HMMR, and EZH2 seemed to be key genes in cancer development." (PMID 39118438, 2024). "Although HMMR has been demonstrated to be upregulated in other cancers, no study has suggested its use as a serologic marker for cancer, especially HCC." (PMID 35456219, 2022). "For example, in the seven cancer types (BLCA, ESCA, HNSC, KIRC, LIHC, STAD and UCEC) with both grade phenotype information and normal control samples, expression of AURKB, BUB1, FOXM1, HMMR, MYBL2, and PLK1 follows the pattern in five cancer types (BLCA, HNSC, KIRC, LIHC, and UCEC)." (PMID 28427185, 2017). "HMMR is classified as a non-motor spindle assembly factor and has been shown to be a critical cell division gene product in immortalized cancer cells." (PMID 28994651, 2017). "HMMR, also known as RHAMM/CD168, has a relatively non-negligible role in neurodevelopment, tissue homeostasis and cancer progression." (PMID 36447119, 2023). "HMMR, also called cluster of differentiation 168(CD168), to date, the role of HMMR in pan-cancer has not yet been explored." (PMID 36704516, 2022).
hematological malignancies (6 papers, 2012 to 2025). "Studies have linked HMMR and its product ‘Receptor for Hyaluronan Mediated Motility’ (RHAMM) to a variety of hematological malignancies and other solid tumors." (PMID 32241274, 2020). "The hyaluronic acid receptors CD44 and the receptor for hyaluronan mediated motility (RHAMM, also known as HMMR and CD168), have been shown to be involved in the pathogeneses of both solid tumors and hematological malignancies." (PMID 35267625, 2022).
gastrointestinal tract cancers (1 paper, 2021). "In the present study, we found that the HMMR was significantly upregulated in gastrointestinal tract cancers, and results from TCGA and GEO datasets and clinical samples further validated the elevated expression of HMMR in CRC tissues." (PMID 34765644, 2021).
HMMR also shares sentences with these, for which no sentence is quoted: pancreatic cancer (12 papers); myelodysplastic syndrome (6); lymphoma (4); Obesity (4); squamous cell carcinoma (4); Arthritis (3); esophageal cancer (3); lymph node metastasis (3); malignant peripheral nerve sheath tumor (3); metastatic tumors (3); pancreatic neuroendocrine tumor (3); rectal cancer (3); seminoma (3); adenocarcinoma (2); astrocytoma (2); B-cell chronic lymphocytic leukemia (2); bladder (2); bladder tumor (2); bladder urothelial carcinoma (2); diabetic kidney disease (2); Granuloma (2); Hepatitis (2); kidney disease (2); lung squamous cell carcinomas (2); osteoarthritis (2); renal cell carcinoma (2); renal fibrosis (2); stomach adenocarcinoma (2); asthma (1); atherosclerosis (1).
A further 63 diseases each share a sentence with HMMR in 1 paper.